METTL14 (methyltransferase 14, N6-adenosine-methyltransferase non-catalytic subunit)
Diseases named in the same sentence as METTL14 in open-access papers (continued):
Sharing a sentence is not in itself a finding about the gene and the disease.
endometriosis (3 papers, 2021 to 2025). The growth of functional endometrial tissue in anatomic sites outside the uterine body. "Despite these limitations, our findings are the first to highlight the critical roles of METTL14 genetic variation in determining susceptibility to endometriosis among Chinese women." (PMID 39831202, 2024). "Consistent with previous studies, our results support that the METTL14 level is reduced in the ectopic endometrium and is associated with an increased risk of endometriosis." (PMID 39831202, 2024). "Our investigation found that common variations in the METTL14 gene were notably linked to endometriosis risk among Chinese women." (PMID 39831202, 2024). "The potential biological functions and mechanisms of the METTL14 gene in the development of endometriosis and infertility deserve further exploration." (PMID 39831202, 2024). "Regarding its role in endometriosis, studies have found that patients with endometriosis have lower levels of m6A in the endometrium than individuals with normal endometrium and that the expression levels of METTL3 and METTL14 are downregulated in ectopic endometria compared with eutopic endometria." (PMID 39831202, 2024).
focal segmental glomerulosclerosis (3 papers, 2021 to 2025). A renal disorder characterized by sclerotic lesions in the glomeruli. "In focal segmental glomerulosclerosis (FSGS), mechanistically dysregulated m6A dynamics contribute to glomerular dysfunction through METTL14-mediated m6A modifications that suppress Sirt1 expression-a nephroprotective deacetylase-in both murine models and human podocytes." (PMID 40895041, 2025).
Hepatic steatosis (3 papers, 2024 to 2025). Steatosis is a term used to denote lipid accumulation within hepatocytes. "m6A methyltransferases METTL3/METTL14 promote the expression of genes related to lipid synthesis (such as Srebp1 and Fasn), exacerbating hepatic steatosis." (PMID 40699703, 2025). "Silencing METTL14 reduced weight gain and mitigated adverse liver function indices, inflammation, hepatic steatosis, and structural damage in NAFLD mice." (PMID 37902450, 2024).
inflammatory bowel disease (3 papers, 2021 to 2025). A spectrum of small and large bowel inflammatory diseases of unknown etiology. "Considering that dysregulation of the balance between Th17 cells and Tregs is strongly associated with the initiation of inflammatory bowel disease (IBD), a reasonable assumption is that METTL14 may be involved in IBD development." (PMID 34869344, 2021). "Inflammatory bowel disease (IBD) exhibits paradoxical m6A regulatory dynamics: METTL3 and FTO demonstrate elevated expression concomitant with METTL14 and HuR downregulation." (PMID 40963968, 2025).
liver disease (3 papers, 2024 to 2025). "Mettl14f/f males were fed a HFD for 10 weeks to induce steatotic liver disease (SLD) and then transduced with AAV8‐TBG‐Cre vector to specifically delete hepatic Mettl14 (AAV8‐TBG‐GFP as control)." (PMID 40278833, 2025).
liver fibrosis (3 papers, 2021 to 2024). "Of note, the authors mentioned that the mechanism of METTL14/GLS2 deficiency-mediated liver fibrosis illustrated in this study is specific to MASH-related fibrosis and may not be applicable to hepatitis B virus (HBV)-induced fibrosis." (PMID 38684673, 2024). "In this study, we reported not only the relevance of METTL3 (a protein, when dimerized with METTL14, responsible for m6A methylation of RNA molecules) to the pathogenesis of liver fibrosis, but its essential role in controlling the stability of lncRNA MALAT1." (PMID 34839365, 2021). "Thirdly, the authors proposed targeting Cx3cr1+Ccr2+MyD88+ Mo-macs-mediated liver fibrosis, which showed improvement upon treatment with the MyD88 inhibitor, ST2825, in Mettl14-KO mice." (PMID 38684673, 2024).
myocardial inflammation (3 papers, 2024 to 2026). "METTL3 and METTL14 deficiencies were induced to evaluate their effect on angiotensin II (Ang II)-induced myocardial inflammation and fibrosis." (PMID 38948064, 2024). "Here, we demonstrate that cardiomyocyte-specific deletion of the m6A methyltransferase METTL14 triggers myocarditis, dilated cardiomyopathy, and premature lethality." (PMID 41993467, 2026).
Nephropathy (3 papers, 2021 to 2025). A nonspecific term referring to disease or damage of the kidneys. "Particularly, METTL14 is reported to be closely associated with kidney diseases, such as renal ischemic reperfusion injury and vascular calcification induced by uremic toxins." (PMID 34580283, 2021). "There are currently 24 known m6A regulatory proteins, but studies on m6A methylation in kidney disease have been limited to four to five enzymes such as METTL14, METTL3 and FTO, and there have been few studies on other enzymes." (PMID 38066436, 2023). "Western blot analysis further supported the evident upregulation of METTL14 protein levels in isolated glomeruli of mice with the two proteinuric kidney disease." (PMID 34580283, 2021). "Interestingly, we identified that the elevation of METTL14 expression was the most evident in the two proteinuric kidney disease models." (PMID 34580283, 2021). "Moreover, METTL3 is more closely associated with kidney disease than METTL14 and FTO, although there are already related drugs to improve renal function and treat renal diseases through METTL3, more in-depth research and exploration can be carried out in this aspect in the future." (PMID 38066436, 2023). "We then detected the mRNA expression of m6A methyltransferases (METTL3, METTL14, and WTAP) and demethyltransferases (FTO and ALKBH5) and found that METTL3 and FTO mRNA expression was upregulated in Pb-induced nephropathy compared with controls." (PMID 40520008, 2025). "METTL3, METTL14 and FTO may play major roles in interstitial fibrosis during UUO nephropathy." (PMID 38066436, 2023).
osteoarthritis (3 papers, 2023 to 2026). A noninflammatory degenerative joint disease occurring chiefly in older persons, characterized by degeneration of the articular cartilage, hypertrophy of bone at the margins and changes in the synovial membrane. "In osteoarthritis patients, the mRNA expression of PRDX3 was negatively correlated with METTL3 mRNA expression, but not with METTL14 mRNA expression." (PMID 40757971, 2025).
rectal cancer (3 papers, 2021 to 2024). A primary or metastatic malignant neoplasm that affects the rectum. "The mechanisms of METTL14’s role in rectal cancer are not only associated with immune system." (PMID 34221955, 2021). "METTL14 expression level is an independent prognostic factor in rectal cancer and is positively correlated with the immune infiltration level." (PMID 34221955, 2021). "Our study identified METTL14 as a potential target for enhancing immunotherapy efficacy in rectal cancer." (PMID 34221955, 2021). "After an evaluation on the expression levels of m6A-related genes and their correlations with the prognosis of rectal cancer patients, we found that METTL14 was the only gene to be significantly correlated with prognosis in rectal cancer patients." (PMID 34221955, 2021). "Although many m6A-related genes were dysregulated in rectal cancer, only METTL14 was related to the prognosis of rectal cancer patients." (PMID 34221955, 2021). "Our work suggests an important role of METTL14 in regulating tumor and immune microenvironment interactions, and identifies METTL14 as a prognostic biomarker as well as a potential target for enhancing the immunotherapy effect in rectal cancer." (PMID 34221955, 2021). "In the univariate cox analysis, RBM15, YTHDF2, and METTL14 were significantly correlated with prognosis in rectal cancer patients." (PMID 34221955, 2021). "Our research preliminarily explores the mechanism by which METTL14 regulates the immune infiltration of rectal cancer and provides inspiration for further research." (PMID 34221955, 2021). "Also, the downregulation of METTL14 and YTHDC2 is associated with the poor prognosis of rectal cancer patients." (PMID 39136000, 2024). "METTL14 downregulation in rectal cancer results in reduced immune cell infiltration and poor prognosis indicating that METTL14 expression level could be utilized as an independent prognostic factor in rectal cancer." (PMID 39136000, 2024). "In conclusion, METTL14 may affect the clinical outcome of rectal cancer patients by regulating the immune infiltration level in the microenvironment." (PMID 34221955, 2021). "The correlation of METTL14 and the immune infiltrates in rectal cancers." (PMID 34221955, 2021). "In sum, METTL14 is a good prognostic factor in rectal cancer." (PMID 34221955, 2021). "Therefore, we further observed the impact of METTL14 expression and m6A modification on the immune infiltration in rectal cancer." (PMID 34221955, 2021). "The expression level of METTL14 in rectal cancer varies according to molecular subtype." (PMID 34221955, 2021). "Since METTL14 functions as an m6A writer gene, its low expression in rectal cancer suggests that the m6A level in rectal cancer cells may be lower than that in normal cells." (PMID 34221955, 2021). "Our study indicates that low expression of the m6A “writer” gene METTL14 in rectal cancer may lead to the downregulation of m6A RNA modification, thus reducing the level of immune cell infiltration and resulting in poor prognosis." (PMID 34221955, 2021). "The results showed that patients with high METTL14 expression had longer OS (p = 0.004), and Cox survival analysis identified the expression level of METTL14 as an independent prognostic factor of patients with rectal cancer." (PMID 34221955, 2021). "Furthermore, we identified METTL14 as a potential target for enhancing immunotherapy efficacy in rectal cancer." (PMID 34221955, 2021). "As an m6A writer gene, METTL14 may affect the survival of rectal cancer patients by downregulating m6A methylation levels." (PMID 34221955, 2021). "In conclusion, our findings demonstrated that the m6A RNA methylation regulators, specifically YTHDC2 and METTL14, were significantly down-regulated and might be potential prognostic biomarkers in rectal cancer." (PMID 34149792, 2021). "Our data support a potential role of METTL14 in rectal cancer with increased antitumor immunity." (PMID 34221955, 2021).
rectal cancer (continued). "Notably, decreased METTL14 expression was found to be significantly correlated with poor prognosis in rectal cancer patients." (PMID 34221955, 2021). "Therefore, we evaluated whether METTL14 expression was related to immune infiltration levels in rectal cancer using the TIMER and GEPIA databases." (PMID 34221955, 2021). "Furthermore, our study indicates that the low expression of the m6A writer gene METTL14 in rectal cancer may lead to a decrease in m6A RNA modification, thus reducing the level of immune cell infiltration and resulting in poor prognosis." (PMID 34221955, 2021). "Our analysis revealed that rectal cancer patients with lower expression of YTHDC2 and METTL14 had a remarkable worse overall survival (P < 0.05)." (PMID 34149792, 2021). "There were 150 rectal cancer tissues and 150 adjacent nontumor tissues in our tissue bank, upon which immunohistochemistry staining for METTL14 was performed using tissue microarrays." (PMID 34221955, 2021). "Compared with adjacent nontumor tissues, the expression levels of METTL14 protein in rectal cancer tissues significantly decreased (p < 0.0001), which was consistent with the results from the public database." (PMID 34221955, 2021).
Stomach Adenocarcinoma (3 papers, 2021 to 2024). "Significant downregulation of METTL14 in gastric adenocarcinoma (STAD) predicted TNM stage in STAD as well as poorer overall survival." (PMID 39289775, 2024).
thyroid cancer (3 papers, 2021). "We showed that METTL14, FTO, and ALKBH5 were down-regulated in most cancers, whereas YTHDF1 and IGF2BP3 were up-regulated in 12 cancer types except for thyroid carcinoma (THCA)." (PMID 33718187, 2021).
allergic asthma (2 papers, 2022 to 2023). A asthma with a basis in a pathological type I hypersensitivity reaction. "We next verified that, compared to 50 normal controls, the abundance of METTL3, METTL14, and YTHDF3 was significantly decreased in PBMCs derived from 55 childhood allergic asthma patients, recruited from the Children’s Hospital of Fudan University." (PMID 37957139, 2023). "The m6A writers METTL14 and the m6A eraser ALKBH5 are decreased significantly both in mRNA and protein level in lung of mice with allergic asthma compared with control." (PMID 36250525, 2022).
Alzheimer disease (2 papers, 2024 to 2025). A progressive, neurodegenerative disease characterized by loss of function and death of nerve cells in several areas of the brain leading to loss of cognitive function such as memory and language. "Tissue-specific delivery systems based on lipid nanoparticles or viral vectors (such as METTL14 activators targeting blood-brain barrier penetration for the treatment of Alzheimer’s disease) will become a research hotspot." (PMID 41194259, 2025). "The role of METTL14 in the development of major neuropsychiatric diseases such as Huntington's disease and Alzheimer's disease has been well researched." (PMID 39046182, 2024).
ankylosing spondylitis (2 papers, 2022 to 2023). An autoimmune chronic inflammatory disorder characterized by inflammation in the vertebral joints of the spine and sacroiliac joints. "METTL14-mediated m6A modification of the ELMO1 3’UTR has been shown to enhance directional migration and osteogenic differentiation of MSCs, thereby improving the therapeutic efficacy in ankylosing spondylitis." (PMID 37865637, 2023).
brain tumors (2 papers, 2017 to 2023). "KD of METTL3 or METTL14 expression reduced mRNA m6A levels, enhanced the growth and self-renewal of GSCs in vitro, and promoted the ability of GSCs to form brain tumors in vivo." (PMID 28297667, 2017). "Again, there are several conflicting reports of m6A regulator expression levels among the different brain tumour entities and non-tumour brain tissue, including ALKBH5, WTAP, METTL14, and YTHDC2." (PMID 36831575, 2023).
Breast Invasive Carcinoma (2 papers, 2020 to 2025). "Within the TCGA Breast Invasive Carcinoma PanCancer Atlas dataset (n = 996) mutations of METTL3, METTL14 and CBLL1 were uncommon, with amplifications being the most common genetic alteration." (PMID 41310336, 2025). "The cBioPortal database was applied to select the top 200 positively co-expressed genes of METTL14 and ZC3H13 based on the data from Breast invasive carcinoma (TCGA, PanCancer Atlas)." (PMID 33363011, 2020).
breast tumor (2 papers, 2020 to 2021). "Besides, we analyzed the downstream carcinogenic molecular mechanisms related to METTL14 and ZC3H13 and their relationship with immune infiltration in breast tumor tissues." (PMID 33363011, 2020). "Furthermore, western blot revealed that the protein levels of METTL3, METTL14, and FTO were significantly lower in seven breast tumor samples randomly selected from RT-qPCR samples, while YTHDF1 and YTHDF3 had higher protein expression compared to adjacent tissues." (PMID 34804948, 2021).
cardiac ischemia (2 papers, 2021 to 2022). "This study was designed to investigate an m6A writer Mettl14 on cardiac ischemia–reperfusion (I/R) injury and uncover the underlying mechanism." (PMID 35004673, 2021).
chronic myelogenous leukemia (2 papers, 2022). "In chronic myelogenous leukemia (CML), METTL3, and METTL14 are upregulated and affect sensitivity to TKI imatinib." (PMID 36226062, 2022).
COVID-19 (2 papers, 2022). A disease caused by infection with severe acute respiratory syndrome coronavirus 2. "At the epigenetic level, arginine alters RNA methylation via methyltransferase like 14 (METTL14) interaction with N6-methyladenosine (m6A), a mechanism documented in COVID-19 pathogenesis." (PMID 35531328, 2022). "COVID-19 patients with elevated expression levels of CBLL1, METLL16, and RBM15B presented elevated expression levels of ALKBH5 while elevated METTL14 and ZC3H13 expression demonstrated a negative association with ALKBH5." (PMID 35655464, 2022).
cytomegalovirus infection (2 papers, 2021 to 2022). A herpesvirus infection caused by Cytomegalovirus. "First, we investigated whether METTL3 or METTL14 (two m6A methyltransferases upregulated by HCMV infection) regulate MCU expression." (PMID 35359726, 2022). "It was observed that the mRNA levels of METTL3, METTL14, YTHDF1, YTHDF2, and YTHDF3 were significantly increased in HAECs following HCMV infection." (PMID 35359726, 2022). "However, silencing METTL3 but not METTL14 resulted in decreased MCU m6A methylation levels under HCMV infection conditions, suggesting that MCU mRNA may be subject to METTL3-dependent m6A methylation." (PMID 35359726, 2022).
dental pulp inflammation (2 papers, 2018 to 2023). "METTL14 mRNA was confirmed to be significantly downregulated in pulpitis samples compared with controls." (PMID 37978362, 2023). "The result indicates that METTL14 may be particularly important in pulpitis, and can be used as a biomarker for the progress of pulpitis, which provides a new idea for future therapeutic targets and drug development of pulpitis." (PMID 37978362, 2023). "The results showed that there were significant differences in the genes ALKBH5, METTL14, METTL3, METTL16, RBM15B and YTHDF1 between normal group and the pulpitis group." (PMID 37978362, 2023). "Validation by qRT-PCR showed that the expression of methylases METTL14 and METTL3 was decreased, thus these two genes may play a key role in pulpitis." (PMID 37978362, 2023).
depression (2 papers, 2023 to 2024). "Considering that METTL3, METTL14, and WTAP are core components of the methyltransferase complex, and FTO and ALKBH5 are major demethylases, it was reported that METTL3, FTO, and ALKBH5 were implicated in the pathology of depression." (PMID 37175269, 2023). "In one study, global m6A methylation is decreased in the whole blood of both human and mice after acute stress, and in another study, ALKBH5 and FTO as m6A demethylases and METTL3, METTL14, and WTAP as m6A methyltransferases are altered in the MDD patients and the depression models." (PMID 38773146, 2024).
epilepsy (2 papers, 2024 to 2025). A brain disorder characterized by episodes of abnormally increased neuronal discharge resulting in transient episodes of sensory or motor neurological dysfunction, or psychic dysfunction. "Collectively, these results indicate that VNS effectively counteracts METTL14 upregulation associated with epilepsy." (PMID 40534269, 2025). "DNA/RNA methylation through the DNMT1/3A and METTL3/METTL14 pathway might be therefore a potential target of VNS therapy for the treatment of epilepsy." (PMID 40534269, 2025). "Vagus nerve stimulation (VNS) reduces the number of SRSs in rats with epilepsy with concomitant decrease of 5‐mC, DNMT1, DNMT3A, METTL3, and METTL14, as well as increase of 5‐hmC." (PMID 40534269, 2025). "We conclude that VNS reduces the number of SRSs in a rat model of epilepsy, concurrently reducing the expression of 5‐mC, DNMT1, DNMT3A, METTL3, and METTL14, as well as the increase of 5‐hmC." (PMID 40534269, 2025).